OR10W1 (olfactory receptor family 10 subfamily W member 1)
Description:
Odorant receptor.
Synonyms: OR10W1P; OR10W1Q; OR11-236; UNQ6469
Tractability: Antibody: UniProt places it where antibodies can reach, with medium confidence; UniProt predicts a signal peptide or a membrane-spanning region; its Gene Ontology location is reachable by antibodies, with medium confidence.
Gene: Protein-coding gene on chromosome 11 (58,266,792 to 58,268,260, reverse strand). Ensembl gene ENSG00000172772.
Subcellular location: Cell membrane
Pathways (Reactome):
Sensory Perception: Expression and translocation of olfactory receptors
Gene Ontology:
Molecular function: odorant binding; olfactory receptor activity; G protein-coupled receptor activity
Biological process: sensory perception of smell; detection of chemical stimulus involved in sensory perception of smell; G protein-coupled receptor signaling pathway
Cellular component: plasma membrane; membrane
Genetic constraint (gnomAD): Loss-of-function variants: 0 observed, 0.56 expected, observed/expected ratio (o/e) 0, 90% interval 0 to 1.82. That is too few expected variants to judge how well the gene tolerates losing a copy. Missense variants: 405 observed, 383.12 expected, observed/expected ratio (o/e) 1.06, 90% interval 0.97 to 1.15. Synonymous variants: 152 observed, 158.77 expected, observed/expected ratio (o/e) 0.96, 90% interval 0.84 to 1.1.
Homologues: Orthologues: macaque OR10W1 (94% identical), dog OR10W1 (85% identical), mouse Or10w1 (80% identical), mouse Or10w3 (79% identical), rat Or10w1 (79% identical), rabbit OR10W1 (63% identical). Paralogues in human: OR10Q1 (53% identical), OR10V1 (47% identical), OR5A1 (43% identical), OR5I1 (41% identical), OR6B2 (41% identical), OR9K2 (41% identical), OR5A2 (41% identical), OR5AU1 (40% identical), OR6B3 (40% identical), OR9G4 (40% identical), OR11L1 (40% identical), OR5B2 (40% identical), and 84 more.